S100A7 (S100 calcium binding protein A7)
Diseases named in the same sentence as S100A7 in open-access papers (continued):
Sharing a sentence is not in itself a finding about the gene and the disease.
breast carcinoma (continued). "Our findings also suggest that S100A7 could be induced by paracrine production of cytokines such as OSM from adjacent ASCs and that its ASC-derived overexpression indicates advanced proliferation, metastasis, and poor prognosis of breast carcinomas, possibly via RAGE activation." (PMID 28629450, 2017). "Additionally, differential expression of mouse S100A7/psoriasin was observed between DMBA and MMTV-neu induced mammary tumors, and a strong trend towards a negative correlation between mouse S100A7/psoriasin and estrogen receptor alpha expression emerged in the DMBA induced mammary tumors." (PMID 15717926, 2005). "Both human S100A7 (psoriasin) and S100A15 transcripts are elevated in ER/PR negative breast cancers; however, hS100A15 protein is detected in all cancer specimens, while hS100A7 protein is sporadically expressed." (PMID 28498804, 2017). "However, it has not been established whether S100A7 may be a target for breast cancer therapy." (PMID 23618129, 2013).
invasive breast carcinoma (15 papers, 2005 to 2024). A carcinoma that infiltrates the breast parenchyma. "Persistent S100A7 expression also occurs in a subset of invasive breast carcinomas and is linked to worse clinical outcome." (PMID 18320059, 2008). "Interestingly, S100A7 over expression (cytoplasmic/nuclear) has been associated with poor patient outcome in ER-negative invasive breast cancer patients." (PMID 20689826, 2010). "The differential regulation of miR-29b by S100A7 in ER-positive and ER-negative breast cancer is supported by the gene expression analysis of TCGA invasive breast cancer dataset." (PMID 25622979, 2015). "c-Jun activation domain-binding protein-1 (Jab1) is a multifunctional signaling protein that previously has been shown to be a master regulator of a poor prognostic gene signature in invasive breast cancer and to mediate the action of S100A7." (PMID 18534028, 2008). "Pathways downstream of S100A7 are also of interest because of this gene's strong association with the ERα- phenotype in DCIS and, when expression persists, in invasive breast cancer." (PMID 18534028, 2008). "In this study, we found that S100A7 expression was negatively correlated with immunomodulators in head and neck squamous cell carcinoma, while was positively correlated in breast invasive carcinoma, liver hepatocellular carcinoma, prostate adenocarcinoma and thyroid carcinoma." (PMID 38499391, 2024). "Although highly expressed in DCIS and generally down-regulated in invasive breast cancer, the expression of psoriasin/S100A7 in both in-situ and invasive breast cancer is correlated with markers of poor prognosis and in invasive carcinoma also with poor clinical outcome." (PMID 15717926, 2005). "To analyze the clinical significance of S100A7 and TLR4 in invasive breast cancer, we analyzed the expression of S100A7 and TLR4 by using the publically available TISIDB database." (PMID 33969603, 2022). "Altogether, our study reports a novel role of LPS in driving S100A7 expression for modulating the expression of TLR4 and RAGE, which demands further exploration of this regulatory axis for drug intervention of invasive breast cancers." (PMID 33969603, 2022). "Taken together, these findings revealed that a high level of S100A7 and low expression of TLR4 could serve as poor prognostic markers for invasive breast cancer patients, especially basal or metastatic breast cancer." (PMID 33969603, 2022). "S100A7 was identified as a differentially expressed gene in ductal carcinoma in-situ (DCIS) but not in invasive breast carcinomas, suggesting its potential role in tumor progression." (PMID 18320059, 2008). "Consequently, elevated levels of S100A7 and reduced expression of TLR4 could serve as indicators of poor prognosis for invasive breast cancer." (PMID 39830522, 2024). "To further analyze the clinical impact of S100A7/cPLA2 signaling in modulating the host immunosuppressive response, we investigated the correlation of these two proteins with the abundance of tumor-promoting CD163+ M2-TAMs using TMAs of invasive breast cancer patients." (PMID 35135586, 2022).
squamous carcinoma (15 papers, 2010 to 2025). "Our study was also supported by an earlier report that showed association of nuclear S100A7 expression with well differentiated squamous cell carcinoma as compared to moderate and poorly differentiated squamous cell carcinomas." (PMID 20689826, 2010). "Aiming to establish biomarkers for bladder cancers, research led by Celis and Ostergaard reported increased levels of Psoriasin (also known as S100A7) in squamous cell carcinomas (SCCs) and urine samples from cancer patients." (PMID 38067168, 2023). "In this study, we identified the function of Lu and Qu on inhibition Src/Stat3/S100A7 signaling in squamous carcinoma cells." (PMID 31731716, 2019). "Our previous study revealed that S100A7 was dramatically induced in several SCC cells and activation of the Hippo pathway significantly promoted S100A7 in epidermoid carcinoma cells." (PMID 27907036, 2016). "Our previous study demonstrated that S100A7 was upregulated in several squamous cell carcinoma (SCC) specimens and was dramatically induced in SCC cells by suspension and dense culture as well as in xenografts." (PMID 27203549, 2016). "S100A7 is highly expressed in squamous cell carcinomas (SCC) and is related to the terminal differentiation of keratinocytes." (PMID 26053695, 2015). "In the present study, we have demonstrated that S100A7 is a common marker of squamous cell carcinomas and displays the cellular heterogeneity in SCC tissues and cells." (PMID 26053695, 2015). "Significant increase in nuclear S100A7 was observed in HNSCC as compared to dysplastic lesions (p = 0.005) and associated with well differentiated squamous cell carcinoma (p = 0.031)." (PMID 20689826, 2010). "Moreover, luteolin reduces Src/STAT3/S100A7 which inhibits the invasion and migration of squamous carcinoma." (PMID 39830909, 2025). "In addition, the migration of squamous carcinoma cells has been found to be modulated by luteolin-induced reduction in expressions and activities of S100A7, Src, and STAT3." (PMID 32224968, 2020). "In this study, high mRNA expression of S100A7 was associated with worse OS in adenocarcinoma, but not in squamous cell carcinoma." (PMID 29607329, 2018). "Taken together, our study demonstrates for the first time that S100A7 not only functions as a facilitator of adenous-squamous carcinoma phenotypic transition in lung cancer cells but also that its expression is differentially regulated by the Hippo-YAP pathway." (PMID 28177901, 2017). "S100A7 is expressed in many squamous cell carcinomas (SCCs)." (PMID 27907036, 2016). "In addition, S100A7 is also strongly expressed in differentiated squamous cell carcinoma and skin carcinoma in situ as well as keratoacanthoma, whereas it is absent in undifferentiated skin basalioma." (PMID 27203549, 2016). "In addition to its antibacterial effects, S100A7 expression is up-regulated in breast cancer and many types of squamous cell carcinomas, including lung, oral cavity, bladder, and skin, and also plays an important role in carcinogenesis and metastasis." (PMID 26053695, 2015).
breast tumor (14 papers, 2008 to 2025). "In this study, we have identified the protein S100A7 as novel molecular target of IGF-1 action in the breast tumor microenvironment, toward increased cancer-associated angiogenesis." (PMID 33557316, 2021). "The IGF1/IGF1R axis primes the breast tumor microenvironment toward the acquisition of an angiogenic phenotype through S100A7/RAGE signaling." (PMID 38892104, 2024). "Expression of S100A7 in breast tumors negatively impacts prognosis through enhancing proliferation, production of proinflammatory molecules (IL-1α, CXC-L1, CXC-L8) and tumor-associated macrophages (TAMs) recruitment." (PMID 39830522, 2024). "S100A7 acts as a paracrine mediator in the breast tumor microenvironment, inducing the proliferation of human vascular endothelial cells and their assembly into vessel-like structures." (PMID 38892104, 2024). "Taken together, these findings suggest that S100A7 and cPLA2 are highly expressed and positively correlated with high-grade breast tumors." (PMID 35135586, 2022). "Using the TISIDB database, we observed that Her2 and basal intrinsic subtypes of breast tumors showed significantly increased expression of S100A7 comparatively to normal breast tissue." (PMID 33969603, 2022). "Our study provides new mechanistic insights on the cross-talk between S100A7/cPLA2 in enhancing breast tumor growth and metastasis by generating an immunosuppressive TME that inhibits the infiltration of cytotoxic T cells." (PMID 35135586, 2022). "discuss the functional role of breast tumor microbiota‐derived lipopolysaccharide, which enhances cancer growth through differentially regulating the S100A7/TLR4 expression." (PMID 33969603, 2022). "S100A7-mediated signaling pathways promote inflammation, which contributes to aggressive breast tumor growth and metastasis." (PMID 35135586, 2022). "In agreement with these clinical observations, we also found that malignant breast tumor tissues showed significantly increased expression of S100A7 as compared to their adjacent normal breast tissues." (PMID 33969603, 2022). "Our results reveal that higher co-expression of S100A7 and cPLA2 aggravate breast tumor growth and distant metastasis by enhancing the iTME and correlates with worse recurrence-free survival." (PMID 35135586, 2022). "We also observed significantly higher expression of both S100A7 and cPLA2 proteins in high-grade malignant breast tumors compared to the low-grade and normal tissues." (PMID 35135586, 2022). "To corroborate the clinical association of S100A7 with TLR4 expression, we analyzed tissue microarrays (TMAs) that contain malignant breast tumors and their adjacent normal control samples." (PMID 33969603, 2022). "Previous reports from others and our group have shown that S100A7 significantly contributes to breast tumor growth." (PMID 35135586, 2022). "Next, we evaluated the relative mRNA expression of S100A7 and cPLA2 in low and high-grade breast tumor tissues using different publically available clinical datasets." (PMID 35135586, 2022). "Altogether, these findings suggest that the IGF-1/IGF-1R axis primes the breast tumor microenvironment toward the acquisition of an angiogenic phenotype through the S100A7/RAGE signaling." (PMID 33557316, 2021). "We established that the IGF-1/IGF-1R axis triggers STAT3-dependent transcriptional activation of S100A7, which acts as a paracrine mediator in the breast tumor microenvironment." (PMID 33557316, 2021). "Recent studies indicated that abnormal expression of S100 proteins – mainly including S100A2, S100A4, and S100A7 – is related to metastasis of breast tumor." (PMID 31244288, 2019). "During breast tumorigenesis and/or progression, several S100 s, including S100A2, S100A4 and S100A7, exhibit altered expression levels based on molecular analysis of breast tumors." (PMID 31795964, 2019).
breast tumor (continued). "Recently, it has reported that S100A7 enhances breast tumor growth and metastasis in MDA-MB-468 ERα (−) cells by activating proinflammatory and metastatic pathways." (PMID 23618129, 2013). "It is highly likely that in breast tumor development, mycoplasma may cooperatively interact with the S100A7/LPS signaling axis, although the precise mechanism and nature of this predicted interaction remain unclear." (PMID 33969603, 2022). "Overall, these findings suggest that the commensal microbiota of breast tissue may enhance breast tumor burden through a novel LPS/S100A7/TLR4/RAGE signaling axis." (PMID 33969603, 2022). "We characterized certain biological actions that might be elicited by S100A7 in the tumor microenvironment, with particular focus on its ability to promote breast tumor angiogenesis, as the angiogenic role of S100A7 is well acknowledged." (PMID 33557316, 2021). "In this cotext, our study highlights that S100A7 may be considered as a novel angiogenic paracrine mediator of the IGF-1/IGF-1R action elicited in breast tumors." (PMID 33557316, 2021). "We have previously identified Jab1 as a mediator of several intracellular and biological effects of S100A7, which itself may promote breast tumor progression." (PMID 18534028, 2008). "Furthermore, higher Jab1 nuclear expression was associated with EGFR+ status in a cohort of ERα- breast tumors, and this relationship was most significant in tumors that expressed both EGFR and S100A7 markers." (PMID 18534028, 2008). "To determine if the S100A7/cPLA2 signaling axis could be exploited as a potential therapeutic target against metastatic breast cancer, we analyzed the clinical utility of cPLA2 inhibitor against breast tumor growth and metastasis using the Hu-PDX mouse model." (PMID 35135586, 2022). "In agreement with our previous results, we observed that S100A7 and PLA2G4A revealed significantly higher expression in high-grade tumors compared to low-grade breast tumor tissues." (PMID 35135586, 2022). "We observed a significant positive correlation between S100A7 and PLA2G4A in distinct signal transduction pathways (r = 0.93) and among different breast tumor samples from pre-and post-chemotherapy (r = 0.59)." (PMID 35135586, 2022). "Our studies also revealed that S100A7 and cPLA2 are positively correlated with the infiltration of CD163+ M2-TAMs in invasive breast tumor tissues." (PMID 35135586, 2022). "Knockdown of S100A7 significantly suppressed ASC-stimulated cell proliferation and migration rate, indicating a possible involvement of S100A7 in the carcinoma–ASC interaction in breast tumors." (PMID 28629450, 2017). "However, further analysis of three of the PDEF induced genes, namely S100A7, CEACAM6 and B7-H4 in primary human breast tumors revealed that only CEACAM6 showed concordance and elevated co-expression with PDEF in primary tumors." (PMID 23592399, 2013). "Since we previously reported over expression of PDEF in breast tumors and since PDEF induces the expression of S100A7, CEACAM6 and B7-H4 in MCF-7 cells, we tested whether these molecules show concordant and elevated co-expression with PDEF in primary breast tumors." (PMID 23592399, 2013). "Therefore, S100A7 may represent a novel effector through which the IGF-1 system executes molecular programs that modulate the breast tumor microenvironment toward the acquisition of negative features (as depicted in the graphical abstract)." (PMID 33557316, 2021).
melanoma (13 papers, 2008 to 2025). A malignant, usually aggressive tumor composed of atypical, neoplastic melanocytes. "Regarding S100A7, two studies analyzing the GEO and TCGA databases demonstrated that it shows high expression in primary melanoma but decreased expression in metastatic melanoma." (PMID 38892279, 2024). "Considering these new findings presented in our study, we suggest a more detailed examination of the possible role of the S100A7 protein as a biomarker in melanoma." (PMID 38892279, 2024). "We found that stronger expression of KRT16 indeed corresponds to stronger expression of S100A7 in our clinical melanoma samples." (PMID 38892279, 2024). "A similar study showed that several S100 family genes, including S100A7, were highly expressed in primary melanoma, but were seen to significantly decrease in metastatic melanoma." (PMID 36553569, 2022). "Within the metal sequestration by the antimicrobial peptides pathway, the S100 family genes S100A7, S100A8, and S100A9 have been linked to tumor growth and metastasis in multiple cancers, including melanoma." (PMID 35008167, 2021). "FGFBP1 was identified as a prometastasis gene in HCC, whereas S100 family genes' expressions, particularly S100A7, were high in primary melanoma samples but low in metastatic melanoma." (PMID 35003328, 2021). "We suggest that staining of the epidermis should be taken into consideration when examining melanoma samples and hope that our study could lead to investigating S100A7 as a potential biomarker in melanoma." (PMID 38892279, 2024). "Therefore, we have decided to examine the association of GLI proteins and their targets, S100A7 and KRT16, in melanoma tissues and investigate their association with the level of immune cell infiltration in melanoma." (PMID 38892279, 2024). "Thus, the association of PRAME, CXCL9, CXCL10, S100A7, S100A8, and S100A9 with melanoma progression is supported by prior studies and commercially available clinical tests." (PMID 35008167, 2021). "S100A7's expression was in relation to tumor invasion, and it may enhance melanoma's early diagnosis." (PMID 35003328, 2021). "This study reveals the genes C7, MMP3, KRT14, LOC642587, CASP7, S100A7 and miRNAs hsa-mir-205 and hsa-mir-203b as the key genomic features that may substantially contribute to the oncogenesis of melanoma." (PMID 31673075, 2019). "Interestingly, one study pointed out that S100A7 can be detected in urine samples of melanoma patients and could potentially be used as a biomarker." (PMID 38892279, 2024). "In addition, numerous studies have reported that S100A7 can not only function within the cell but can also be secreted and detected in serum (lung squamous cell carcinoma), saliva (oral squamous cell carcinoma), urine (melanoma), and other body fluids." (PMID 34323409, 2021). "Before using clinical melanoma samples, we successfully validated KRT16 and S100A7 as GLI targets on different in vitro models of melanoma cell lines, as their expression was strongly upregulated upon overexpression of all three GLI proteins." (PMID 38892279, 2024). "We present here for the first time that S100A7 and KRT16 are transcriptional targets of GLI proteins in melanoma." (PMID 38892279, 2024). "The myPath Melanoma Test utilizes the expression of 14 signature genes, including PRAME, CXCL9, CXCL10, S100A7, S100A8, and S100A9, and nine reference genes to distinguish BN from CMM." (PMID 35008167, 2021). "S100A4 levels are lower in metastatic melanoma compared with primary tumors, while S100A7, S100A8, and S100A9 levels appear to be higher in malignant melanoma compared with normal melanocytes." (PMID 19859558, 2010). "Genes such as KRT14, GJA1, S100A7, S100A9, and EHF were higher in most melanomas while genes such as CITED-1, GDF15, QPRT, OCA2, c-MET and MME were more highly expressed in NHEM." (PMID 18442402, 2008).
melanoma (continued). "By contrast, S100A7 shows a much wider expression pattern than S100A9, but despite its ability to promote cell proliferation, migration, invasion, and tumor metastasis in cervical, breast, and ovarian cancer, S100A7 has not previously been implicated in melanoma pathogenesis." (PMID 36139698, 2022).